DLL3 (delta like canonical Notch ligand 3)
Diseases named in the same sentence as DLL3 in open-access papers (continued):
Sharing a sentence is not in itself a finding about the gene and the disease.
cancer (59 papers, 2009 to 2026). A tumor composed of atypical neoplastic, often pleomorphic cells that invade other tissues. "The roles of miR-508-5p, DLL3, and their involvement in cancer development and progression are closely linked." (PMID 40066092, 2025). "This review aims to explore the mechanisms, challenges, and future opportunities associated with therapies targeting DLL3 for cancer treatment." (PMID 40284515, 2025). "All JAG, DLL, and NOTCH families genes, except DLL3, showed a similar correlation trend with hallmark signatures across various cancer types." (PMID 39074091, 2024). "Our results demonstrate that, in the vast majority of cancer types, levels of immune cell infiltration were significantly linked with DLL3 expression." (PMID 37179118, 2023). "MMR gene expression was clearly and significantly inversely linked with DLL3 levels in the majority of cancers, with the exception of LIHC." (PMID 37179118, 2023). "Interestingly, in contrast to the relatively consistent associations we observed between high DLL3 expression and poor overall survival across NENs, we found differential patterns with real-world outcomes across different cancer types." (PMID 39874041, 2025). "HPN328, a tri-specific T cell activating construct (TriTAC®) targeting DLL3, is undergoing a Phase I/II trial to assess safety, tolerability, and pharmacokinetics, both as monotherapy and in combination with atezolizumab, in patients with advanced cancer associated with DLL3 expression." (PMID 38797752, 2024). "However, as RB1-loss is typically found in neuroendocrine marker expressing SCLC this might point to the associated DLL3-expression in this set of carcinomas." (PMID 31109352, 2019). "The bispecific antibody tarlatamab recruits T cells to cancers expressing the neuroendocrine epitope delta-like ligand 3 (DLL3)." (PMID 41532856, 2026). "DLL3’s molecular heterogeneity across SCLC subtypes highlights its potential as a diagnostic and prognostic biomarker in personalized cancer care." (PMID 40496850, 2025). "Lastly, we explored the potential utility of DLL3 as a precision therapy target in cancer types outside of NENs." (PMID 39874041, 2025). "Emerging evidence reveals DLL3 as a pan-cancer oncoprotein with context-dependent therapeutic implications across diverse malignancies." (PMID 40496850, 2025). "DLL3, a membrane-bound protein of the Notch ligand family, is aberrantly expressed in several cancers, including SCLC." (PMID 40422520, 2025). "Numerous studies have consistently shown that DLL3 is an attractive target for cancer immunotherapy." (PMID 40066092, 2025). "The biological characteristics of DLL3 and its role in the Notch signaling pathway are introduced first, delving into the role of DLL3 in tumorigenesis and cancer progression." (PMID 40284515, 2025). "In HNSC, both expression and DEG enrichment of JAG1, DLL1, and NOTCH2 significantly increased after anti-cancer therapy, while DLL3 and NOTCH4 significantly decreased." (PMID 39074091, 2024). "DLL3 (Delta-like protein 3) is a protein that is highly expressed in SCLC but is minimally expressed in other cancer types and normal tissues." (PMID 39451714, 2024). "In 18 different types of cancers, DLL3 expression was linked to TMB and MSI, whereas in KIRC, LIHC, and PAAD, DLL3 expression and TME were correlated." (PMID 37179118, 2023). "According to the results of the ESTIMATE algorithm scores for 34 genes, DLL3 expression was strongly positively connected with immune scores as well as with stromal scores in a pan-cancer analysis, with the exception of DLBC, LAML, and THYM." (PMID 37179118, 2023). "Subsequent examination of our data showed that DLL3 expression was significantly correlated with immune cell infiltration levels in the majority of cancer types." (PMID 37179118, 2023). "Further, DLL3 was a low-risk gene in LGG, THCA, UVM, LAML and PAAD, while it was a high-risk gene in other types of cancer." (PMID 37179118, 2023).
cancer (continued). "This suggests that further research is necessary to determine the precise function of DLL3 in each type of cancer." (PMID 37179118, 2023). "Although various researchers have shed light on the function of DLL3 in tumors, their descriptions have only been applied to a certain types of cancer." (PMID 37179118, 2023). "The cell surface Notch ligand delta-like 3 (DLL3) has recently emerged as a therapeutic target in cancer." (PMID 35267433, 2022). "In other cancer types, gene silencing of DLL3 induces intrinsic apoptosis, resulting in significant growth inhibition." (PMID 36338696, 2022). "In a recent study, 63 patients with SCLC underwent immunohistochemistry (IHC) for DLL3: 52 patients (83%) were positive for DLL3 expression, with 20 patients (32%) showing high expression of DLL3 (positive in at least 50% of cancer cells)." (PMID 36530878, 2022). "In a phase I clinical trial, Rova-T was more effective in SCLC with DLL3 overexpression (defined as expression in at least 50% of cancer cells by immunohistochemistry) compared with SCLC with a low level of DLL3 expression." (PMID 34692726, 2021). "This characteristic makes DLL3 an attractive target for cancer therapy." (PMID 40284515, 2025). "This review aims to summarize the biological role of DLL3, its expression patterns, signaling mechanisms, and its potential role as a therapeutic target in cancer treatment, concluding with an outlook on DLL3-targeted therapies for the treatment of tumors that express it." (PMID 40284515, 2025). "Competing strategies such as bispecific T-cell engagers (e.g., DLL3-targeting agents), antibody-drug conjugates, and cancer vaccines offer alternative mechanisms for engaging the immune system, often with less complex manufacturing and more manageable toxicity profiles." (PMID 41200177, 2025). "Notably, the NPC/GPC-like cancer cells are marked by ASCL1 or its direct target genes (DLL3, HES5) and are resistant to TMZ treatment." (PMID 39609428, 2024). "For instance, DLL3 is more highly expressed in metastatic CRC tumors than in primary lesions, and its diagnostic role with prognostic value and therapeutic potential for anti-cancer therapy has been suggested." (PMID 39074091, 2024). "Relevant alterations range from genetic aberrations (e.g. AR-gain or mutations) to transcriptional changes such as alternative splicing (e.g. AR-V7), expression of PSMA and SLFN11, or upregulation of neuroendocrine markers (e.g. SYP, CHGA, NCAM1, and DLL3) in cancers cells." (PMID 39550585, 2024). "Furthermore, across numerous cancer types, DLL3 expression was related to TMB, MSI, and immune cell infiltration." (PMID 37179118, 2023). "Our findings demonstrate that DLL3 is crucial for cancer immunity." (PMID 37179118, 2023). "DLL3 expression across numerous cancer types was related to TMB, MSI, and immune cell infiltration." (PMID 37179118, 2023). "Of note, the highest difference in DLL3 expression in cancer and normal tissues was for GBM." (PMID 37179118, 2023). "Higher expression of DLL3 or IL-33 could lead to a lower survival rate based on University of California, Santa Cruz Xena Functional Genomics Explorer and The Cancer Genome Atlas data set." (PMID 35382168, 2022). "Many studies have shown that DLL3 played a significant prognosis value in patients with cancer." (PMID 32847588, 2020). "CD133 is a surface marker of cancer stem cells, and thus, DLL3 upregulation in CD133+ peripheral cells may affect hepatocarcinogenesis in HCV-associated HCCs." (PMID 29555949, 2018). "Thus, understanding the role of DLL3 in various cancers is crucial." (PMID 40066092, 2025). "It is worth noting, however, the associations we found with high DLL3 expression and the prevalence of genomic alterations associated with NECs versus NETs, particularly considering the propensity of the latter with GEP-NENs versus most prostate and bladder NENs representing carcinomas." (PMID 39874041, 2025).
cancer (continued). "Moreover, the tri-specific DLL3-targeting T-cell engager, which additionally targets the albumin binding domain to extend its half-life, is currently undergoing phase I / II clinical trials (NCT04471727) in patients with DLL3-associated cancers." (PMID 39342365, 2024). "Interestingly, DLL3 decreased after anti-cancer therapy, contrary to DEG enrichment of other genes." (PMID 39074091, 2024). "By analyzing public Gene Expression Omnibus (GEO, GSE149507) and Cancer Cell Line Encyclopedia (CCLE) databases, we preliminarily demonstrated that DLL3 is highly expressed in SCLC tissues and cell lines." (PMID 40075480, 2025). "Tarlatamab (AMG 757) is a half-life extended BiTE designed to specifically bind DLL3 on cancer cells and CD3 on T cells, resulting in T-cell-dependent killing of cancer cells with DLL3 expression in the SCLC patient-derived xenograft models." (PMID 37422534, 2023). "As there are many Notch ligands—Jag1, Jag2, DLL1, DLL3, and DLL454—we wanted to identify which Notch ligand(s) is/are involved in stemness induction in cancer cells." (PMID 34911937, 2021). "Incremental CTC count has been reported using a method based on the specific telomerase activation of cancer cells (OBP-401), while folate receptor-positive CTCs, CK-19 mRNA-positive CTC, or DLL3+/CD45− CTCs, decrease during response." (PMID 34066817, 2021). "The selective expression of Dll3 in postnatal mouse NEB cells, both at the gene expression and protein level, is certainly intriguing with respect to the cancer stem cell discussion." (PMID 28482837, 2017). "DLL3 acts as a Notch ligand that is characterized by a DSL domain, EGF repeats, and has also been studied in cancers." (PMID 26771237, 2016). "The transcripts were selected to inform about diverse resistance mechanisms (AR-V7 expression, neuroendocrine transdifferentiation), druggable targets and predictive markers (PSMA, DLL3, SLFN11), and cancer-related processes such as epithelial mesenchymal transition (VIM, KRT)." (PMID 39550585, 2024). "DLL3 expression is not commonly found in normal adult tissues, which makes it an attractive target for anti-cancer therapies." (PMID 39392394, 2024). "The conjugated product was subsequently tested on 293T cancer cells with and without DLL3 (Delta-Like 3 Protein) expression." (PMID 39201338, 2024). "The relationship between DLL3 and different malignancies has not yet been investigated in a pan-cancer analysis." (PMID 37179118, 2023). "Since the co-culture was performed by transwell and DLL3-overexpressed cancer cells had no direct contact with macrophages, DLL3 overexpression in cancer cells affected macrophages via a unique mechanism." (PMID 35382168, 2022). "Additionally, we observed that METTL3 is involved in the modulation of Notch signaling pathway (including METTL3 DLL3, HES1, and NOTCH3 genes) (q-value < 0.05), which plays an important role in tumorigenesis and cancer development." (PMID 34589481, 2021). "Furthermore, emerging CSRs (EGFR, DLL3, and keratin 1) that may support next-generation TDD platforms for cancer treatment are also highlighted." (PMID 41900872, 2026). "Successful preclinical NIR-PIT studies against cancer and cancer-stem like cell antigens have been performed against more than 20 different molecular targets expressed on different cancers including EGFR, HER2, PSMA, CD25, GPC3, mesothelin, CD133, CD44, CEA, DLL3, PD-L1, and others." (PMID 38658501, 2024). "Setting the hallmarks of cancer as the reference gene sets, GSEA demonstrated that hallmarks such as epithelial-mesenchymal transition and signaling pathways like NOTCH signaling, KRAS signaling, and TNFα signaling via NF-κB were significantly enriched in the low DLL3 expression group." (PMID 36338696, 2022).
cancer (continued). "In summary, macrophages could induce the activation of DLL3-dependent Notch1/Notch2 signaling, the upregulation of IL-33, and the degradation LG3BP and HSPA8, resulting in enhanced cancer-cell proliferation and elevated IL-1β, IL-12, and IL-10 secretion by macrophages." (PMID 35382168, 2022). "ASCL1 KO tumors developed a poorly differentiated carcinoma without detectable expression of the NE lineage markers SYP, INSM1, or DLL3 but showed higher expression of NOTCH2, HES1, and KRT8." (PMID 39024561, 2024).
adenocarcinoma (10 papers, 2021 to 2025). A common cancer characterized by the presence of malignant glandular cells. "The only NEC positive for SEZ6 was a poorly differentiated adenocarcinoma with variable neuroendocrine differentiation; it was strongly positive for DLL3 and was also moderately positive for SEZ6 in 20% of the cells (H-score 40)." (PMID 40699376, 2025). "In doing so, we observed significantly higher expression of DLL3 in NENs derived from both the lung and prostate compared with site-matched adenocarcinomas (ADCs)." (PMID 39874041, 2025). "Because NEPC typically arises as a consequence of lineage transformation from PRAD, we next looked at DLL3 expression in our adenocarcinoma cohort and found clear evidence of DLL3 expression within subsets of cells within CRPC–adenocarcinoma tumors." (PMID 38645034, 2024). "Aurora kinase A (AURKA), a G2→M regulating cell cycle kinase, and delta-like protein 3 (DLL3), a cell surface notch signal inhibiting ligand, are other examples of proteins enriched in NEPC and its small-cell variant compared to adenocarcinoma." (PMID 35205640, 2022). "DLL3 expression was tied to a better OS in low differentiation adenocarcinoma, HR 0.61 (0.39–0.94), p = 0.024." (PMID 36071128, 2022). "In contrast, the two initial adenocarcinoma samples stained negative for DLL3 (0 intensity, 0% expression)." (PMID 41256964, 2025). "The remainder of the CTC samples in this cohort had low or no DLL3 expression at either the protein or transcriptional level, including examples of both adenocarcinoma and histologic NEPC." (PMID 39912912, 2025). "One previous analysis of DLL3 expression in SCLC transformed tissue found DLL3 expression in 93% of specimens, which was absent in baseline adenocarcinoma samples." (PMID 41256964, 2025).
lung (4 papers, 2021 to 2025). "Nine of 11 lung NETs expressed DLL3 (H-score 191), while only two had focal weak staining for SEZ6 (H-score 45)." (PMID 40699376, 2025). "Stratifying lung NENs by histologic annotation, we identified increased expression of DLL3 across lung NET grades, and increased proportions of DLL3-high samples throughout, with 58.3% of grade 1 lung NETs being defined as DLL3-high in comparison to 82.1% of large cell NECs." (PMID 39874041, 2025). "However, in their study, only a relatively small percentage of lung NETs had low expression of DLL3." (PMID 34568063, 2021).
gastrointestinal tumors (2 papers, 2022 to 2023). "However, the literature we found only a few data have analyzed the relationship between DLL3 and prognosis in gastrointestinal tumors, and the expression of DLL3 in GC and its effect on prognosis have not been reported." (PMID 36071128, 2022).
DLL3 also shares sentences with these, for which no sentence is quoted: metastatic disease (3 papers); brain tumors (2); cholangiocarcinoma (2); kidney cancer (2); non-small cell lung carcinoma (2); renal carcinoma (2); acute myeloid leukemia (1); astrocytoma (1); autosomal recessive spondylocostal dysostosis (1); B cell lymphomas (1); benign prostate tumors (1); bladder cancer (1); bladder urothelial carcinoma (1); cardiac hypertrophy (1); cyclopia (1); cyst (1); desmoid tumor (1); dysostosis (1); gastric adenocarcinoma (1); gastroenteropancreatic neuroendocrine neoplasms (1); gastroenteropancreatic neuroendocrine tumours (1); genetic disorder (1); hematological malignancies (1); hepatitis B (1); hepatitis C (1); Hyperglycemia (1); medulloblastoma (1); metastatic melanoma (1); neurodevelopmental disorder (1); pancreatic adenocarcinoma (1).
A further 11 diseases each share a sentence with DLL3 in 1 paper.